TEAD4 (TEA domain transcription factor 4)
Diseases named in the same sentence as TEAD4 in open-access papers (continued):
Sharing a sentence is not in itself a finding about the gene and the disease.
lung carcinoma (11 papers, 2016 to 2025). "In lung cancer, TEAD4 is upregulated and promotes the proliferation, migration, and tumorigenesis of LUAD cells by transcriptionally activating and phosphorylating extracellular signal-regulated kinase (ERK) proteins." (PMID 39735666, 2025). "The TCGA database study found that people with lung cancer had a higher TEAD4 overexpression and a poorer overall survival rate." (PMID 39187525, 2024). "miR-512-5p was also able to augment cisplatin-induced apoptosis and inhibit cell migration in lung cancer cells by targeting TEAD4." (PMID 33795521, 2021). "Further genomic or proteomic studies in TEAD4‐silencing or TEAD4‐overexpressing lung cancer cells may better illuminate our hypothesis." (PMID 29667772, 2018). "It seems that TEAD4 functions distinctively between digestive system tumours and lung cancers." (PMID 29667772, 2018). "To test this possibility, we measured the relative levels of TEAD4 in a panel of lung cancer cells." (PMID 27291620, 2016). "The global transcriptomic network analysis highlighted the impact of five TFs, SOX4, TCF3, TEAD4, ETV4, and FOXM1, in gut and lung cancer." (PMID 39228892, 2024). "When transfecting ESF-TEAD4 in YAP stably expressed lung cancer cells, H157 and A549, we found that the ESF-TEAD4 specifically shifted TEAD4 splicing towards the short isoform as compared with control ESF." (PMID 27291620, 2016). "To further validate the role of IGFBP7 on the c-Fos/YAP/TEAD1/TEAD4 signaling axis in human lungs, we analyzed the expression of IGFBP7/c-Fos/YAP/TEAD1/TEAD4 in lung tissues of ARDS patients and para-cancerous tissues of lung cancer patients collected previously." (PMID 38840498, 2024). "Additionally, lung adenocarcinoma cells from NSCLC, the most frequent form of lung cancer, were selected to verify that YAP/TEAD4/NRP1 had an effect on radiation resistance in NSCLC cells but other lung cancer classification have not been well explored." (PMID 39187525, 2024).
bladder cancer (9 papers, 2019 to 2025). "In our study, TEAD4 was upregulated in the high-risk group, indicating that it might act as an oncogene in bladder cancer, which was consistent with the previous research and its positive association with the abundance of immune infiltration." (PMID 37968767, 2023). "The multivariate Cox regression analysis showed that TEAD4 is an independent prognostic factor for bladder cancer." (PMID 35602596, 2022). "In summary, our study reveals that the crosstalk between AMPK and Yap1/TEAD4 plays an important role in bladder cancer inhibition by metformin and that it is a critical cell cycle regulator that downregulates CCNE1 and CCNE2 directly." (PMID 31455378, 2019). "Studies have demonstrated that TEAD4 mediated EMT of bladder cancer through PI3K/Akt pathway, indicating that TEAD4 could serve as an effective biomarker for prognosis prediction and a potential target for the treatment of metastatic bladder cancer." (PMID 37968767, 2023). "It was found that TEAD4 high expression group was enriched in multiple immune related pathways, and various infiltrated immune cells were related to TEAD4 expression, revealing that it was a potential immunoregulator in bladder cancer." (PMID 37968767, 2023). "Furthermore, knockdown of TEAD4 Inhibits bladder cancer cells migration and invasion." (PMID 35602596, 2022). "One study demonstrated that the TEAD4 transcription factor, located in the TEA domain, triggers epithelial-mesenchymal transition (EMT) in bladder cancer through the PI3K/Akt pathway." (PMID 40635786, 2025). "Considering the regulatory role of YAP1/TEAD4 in KIF4A transcription in esophageal squamous cell carcinoma and the role of TEAD1 in chemoresistance of bladder cancer, we sought to investigate whether YAP1/TEAD1 is involved in KIF4A dysregulation in UBC." (PMID 37039264, 2023). "As the key component of Hippo signaling, we therefore suggest that the Yap1/TEAD4/CCNE1/2 could be a potential therapeutic axis in BLCA, via which metformin can be a potential candidate for the development of novel treatment strategies for human bladder cancer." (PMID 31455378, 2019).
ovarian carcinoma (9 papers, 2014 to 2025). A malignant neoplasm originating from the surface ovarian epithelium. "The co-expression of YAP and TEAD4 in ovarian cancer tissues was even more dramatically associated with poor patient survival." (PMID 24622501, 2014). "Correlation analysis results showed that YAP and pYAP were positively correlated with TEAD1-4 expression, and were most closely correlated with TEAD4 expression.An association analysis using 45 ovarian cancer patient samples was done in which we ranked Kaplan-Meier survival estimates." (PMID 24622501, 2014). "Interestingly, YAP expression was positively correlated with TEAD4 expression and their co-expression was closely associated with poor ovarian cancer patient survival." (PMID 24622501, 2014). "We further investigated if TEAD4 alone might be associated with ovarian cancer patient survival." (PMID 24622501, 2014). "By contrast, overexpression of YAP/TEAD4 contribute to chemo-drug resistance, migration, and growth of ovarian cancer." (PMID 35602596, 2022). "More importantly, among four TEAD members, TEAD4 is co-expressed with YAP in all subtypes of ovarian cancer." (PMID 35602596, 2022). "It has been reported that copy number increase and overexpression of TEAD4 are detected in ovarian cancer and fallopian tube carcinoma." (PMID 35602596, 2022). "We evaluated the usefulness of YAP, TEAD4, SMAD2, SMAD3, H2A.X, ALD1A1, CD71, TKT and TKTL1 as diagnostic or prognostic markers in patients with ovarian cancer." (PMID 34205023, 2021). "We categorized TEAD4-expressing ovarian cancer samples into those with weak and strong expressions and compared these with patient prognosis." (PMID 24622501, 2014). "Specifically, we showed for the first time that high YAP expression levels were positively correlated with TEAD4 gene expression, and their co-expression was a prognostic marker for poor ovarian cancer survival." (PMID 24622501, 2014). "Further, high YAP and TEAD4 expression is a prognostic marker for ovarian cancer progression and a potential target for ovarian cancer treatment." (PMID 24622501, 2014). "Taken together, these findings indicate that YAP is a key ovarian cancer oncogene and that YAP/TEAD4 co-expression may be a predictor of a poor prognosis for human ovarian cancer." (PMID 24622501, 2014). "Thus, high YAP/TEAD4 levels could be a predictor for determining ovarian cancer malignancy levels and for estimating the prognosis of these patients." (PMID 24622501, 2014). "Taken together, these results indicated that YAP and TEAD4 were two significant independent markers for poor patient survival and their combined evaluation might be a strong independent predictor of disease-specific survival for ovarian cancer patients." (PMID 24622501, 2014). "Previous studies have shown that RAD21 amplification epigenetically interacts with YAP/TEAD4 transcriptional co-repressors, recruiting the NuRD complex to inhibit interferon (IFN) signaling and promote immune evasion in ovarian cancer." (PMID 40406120, 2025). "It is reported that the expression of YAP and TEAD4 is positively correlated and the coexpression of YAP and TEAD4 is tightly relevant to the poor prognosis of ovarian cancer." (PMID 37799806, 2023). "YAP expression levels are positively correlated with TEAD4 (the c-terminal region of transcriptional enhancer factor TEF-1) levels and their co-expression is a prognostic marker for poor ovarian cancer survival." (PMID 35052372, 2021). "A significantly higher statistically significant level of mRNA expression was found in the ovarian cancer group for YAP and TEAD4 (p = 0.003 and p = 0.006, respectively)." (PMID 34205023, 2021). "We evaluated the differences in the expression of the YAP, TEAD4, SMAD2, SMAD3, H2A.X, ALD1A1, CD71, TKT, and TKTL1 in ovarian cancers and benign cysts." (PMID 34205023, 2021). "The YAP, TEAD4, and ADH1A proteins appear to be promising biomarkers in the diagnosis of ovarian cancer." (PMID 34205023, 2021).
ovarian carcinoma (continued). "YAP, TEAD4, and ADH1A proteins appear to be promising biomarkers in the diagnosis of ovarian cancer." (PMID 34205023, 2021). "A significantly higher level of mRNA expression was found in the ovarian cancer group for YAP and TEAD4 (p = 0.004 and p = 0.003, respectively)." (PMID 34205023, 2021). "In ovarian cancer initiated cells, TEAD1 and TEAD4 were found to be expressed at significantly higher levels than in differentiated ovarian cancer cells." (PMID 31718559, 2019). "In ovarian cancer initiated cells (OCICs), TEAD1, TEAD3 and TEAD4 were found to be expressed at significantly higher levels than in differentiated ovarian cancer cells." (PMID 26805820, 2016). "Thus, YAP and TEAD4 might biochemically function together in ovarian cancer progression, and YAP-TEAD4 co-expression may be important for assessing ovarian cancer patient outcomes." (PMID 24622501, 2014).
liver cancer (8 papers, 2018 to 2025). An epithelial or non-epithelial malignant neoplasm that arises from the liver. "HNF4α directly binds to TEAD4, competing with YAP1 for TEAD4, stalling liver cancer cell proliferation." (PMID 40066231, 2025). "VGLL4 interrupts YAP/TEAD4 complex in liver cancer and TEAD/TCF4 (Transcription Factor 4) complex to suppress Wnt/β-catenin downstream targets." (PMID 35602596, 2022). "It is worth mentioning that TEAD4 also can modulate the liver cancer progression in a YAP-independent manner." (PMID 35602596, 2022). "TEAD4 promotes liver cancer cell proliferation, migration, and tumor growth." (PMID 38102321, 2023). "The expression of TEAD4 is increased in many types of cancer, including breast and liver cancer." (PMID 36830634, 2023). "In liver cancer, TEAD4 is not the only TEAD member implicated in oncogenesis." (PMID 35602596, 2022). "Together with TEA domain transcription factor 4 (TEAD4), YAP transcriptionally regulates PAI-1 expression in human and murine liver cancer cell lines." (PMID 33097058, 2020). "Notably, TEAD4 shows contrasting expression patterns in NAFLD and liver cancer, suggesting its regulatory role in the progression from NAFLD to liver cancer." (PMID 38102321, 2023). "YAP/TEAD4 also binds FOXM1 (Forkhead Box M1) to induce the chromosome instability and targets PAI-1 (plasminogen activator inhibitor-1) to control the senescence in liver cancer." (PMID 35602596, 2022). "In liver cancer cells, integrin αV dose not bind to YAP, but instead binds to the promoter together with TEAD4 as a target gene for TAZ." (PMID 36613819, 2022).
lung adenocarcinoma (7 papers, 2018 to 2025). A carcinoma that arises from the lung and is characterized by the presence of malignant glandular epithelial cells. "Several studies have shown the tumorigenesis role of transcriptional enhancer associate domain (TEAD) proteins; here, we initially explored expression, function and signalling mechanisms of TEAD4 in lung adenocarcinoma (LAD)." (PMID 29667772, 2018). "miR‐6839‐3p is a novel tumour‐suppressor functions by targeting TEAD4 in lung adenocarcinoma." (PMID 29667772, 2018). "TEAD4 is up‐regulated in lung adenocarcinomas and correlated with unfavourable clinical outcome." (PMID 29667772, 2018). "TEAD4 silencing markedly attenuated cell migration and invasiveness in lung adenocarcinoma." (PMID 30459528, 2018).
melanoma (7 papers, 2018 to 2025). A malignant, usually aggressive tumor composed of atypical, neoplastic melanocytes. "In addition, patients with melanoma who expressed lower levels of NF2, TEAD3, and TEAD4 were associated with longer OS than those who expressed lower levels of NF2, TEAD3, and TEAD4." (PMID 38515849, 2024). "Also, TEAD4 transcript level was found decreased after Bcl-2 depletion in melanoma." (PMID 38755629, 2024). "Of the 62 melanoma cell lines in the DepMap Portal, 17 are dependent upon TAZ, 2 are dependent upon YAP, 9 are dependent upon TEAD1, and 1 is dependent upon TEAD4." (PMID 38473214, 2024). "We selected TEAD1 and TEAD4 for analysis because they are the predominantly expressed TEAD paralogs in many cancer cell lines, including NCI-H226 and MSTO-211H58 and in SOX10 KO melanoma cells." (PMID 41193428, 2025).
glioma (6 papers, 2016 to 2025). A benign or malignant brain and spinal cord tumor that arises from glial cells (astrocytes, oligodendrocytes, ependymal cells). "Additionally, high TEAD4 DNA copy number variation with isocitrate dehydrogenase mutations in low grade glioma correlates with a shorter overall survival and disease-free survival." (PMID 35602596, 2022). "The Co-IP assay confirmed direct interaction of YAP1 with TEAD4 in glioma cells cultured in a flask." (PMID 33408794, 2021). "In the meantime, our study discovered that 1p19q co-deletion would downregulate TEAD4 expression in glioma." (PMID 33889755, 2021). "Mass spectrometry analysis showed that TEAD4 may be the main binding partner for YAP1 as a co‐activator protein in glioma." (PMID 33408794, 2021). "Based on these, the expression of TEAD4 would take on different roles in glioma prognosis depending on whether the patient is carrying IDH variation." (PMID 33889755, 2021). "As shown in Co-IP we have found that TAZ also bind to TEAD4 in glioma." (PMID 27764783, 2016). "In high grade gliomas, TAZ binds TEAD4 and modulates the expression of cyclin D1, Bcl-2 and MMP-9 (Matrix metallopeptidase 9), leading to cell proliferation and migration." (PMID 35602596, 2022). "In glioma, only TEAD2 has been reported to bind with TAZ to regulate transcription of a majority of mesenchymal genes, while TEAD4 has not been reported to bind with TAZ in glioma cell up to now." (PMID 27764783, 2016). "Incorporating TEAD4 CNVs might better stratify the patients with LGG, which would provide new biomarkers for establishing new molecular classification systems for further precision medicine in glioma." (PMID 33889755, 2021).
neuroblastoma (6 papers, 2015 to 2024). Neuroblastoma (NB) is the most common solid, extracranial childhood tumor. "The results of the Koster study showed that 10 protein transcription modules centered on the positive feedback loop of TEAD4-MYCN became regulatory drivers of high-risk subtypes associated with the expansion of invasive neuroblastoma subtype (MYCN)." (PMID 39575432, 2024). "Another candidate co-regulator is TEAD4, which drives the MYCN-induced transcription network in MYCN-amplified neuroblastomas, although we were unable to detect TEAD4 in a MYCN-transduced fetal retina." (PMID 33425720, 2020). "PLK-1, CDK-1, PIK3CA, ATF4, TEAD4 and ALYREF could enhance MYCN protein stability and sustain MYCN expression in neuroblastoma." (PMID 35820898, 2022).
prostate carcinoma (6 papers, 2020 to 2024). A carcinoma that arises from epithelial cells of the prostate gland. "Here, the authors show in prostate cancer cells that arginine globally upregulates nuclear-encoded oxidative phosphorylation genes by altering histone acetylation and retaining TEAD4 in the nucleus to transactivate genes." (PMID 33893278, 2021). "Furthermore, TEAD4 is also associated with the disease progression predictor of prostate cancer, Gleason score." (PMID 33893278, 2021). "Recently, it has been reported that L-arginine exerts an epigenetic regulation over TEA-like domain 4 (TEAD4) in prostate cancer cells." (PMID 36982390, 2023). "At the early stage, ETS-regulated gene (ERG) induces YAP expression, which drives the YAP/TEAD4 transcriptional complex to induce the development of prostate cancer." (PMID 35602596, 2022). "Our work thus not only provides fundamental understanding of TEAD4’s functions in mitochondrial biology but also uncovers TEAD4 as a potential intervention target for prostate cancer." (PMID 33893278, 2021). "Recent work further showed that TEAD4 expression correlated with prostate cancer progression." (PMID 35602596, 2022). "Given the strong correlation of TEAD4 expression and prostate carcinogenesis, targeting TEAD4 may be beneficially used to enhance arginine-deprivation therapy and prostate cancer therapy." (PMID 33893278, 2021). "The data collectively point to TEAD4 as a progression factor for prostate cancer." (PMID 33893278, 2021). "Moreover, previous reports have indicated that arginine has the ability to directly activate the nutrient-sensing kinase, mammalian target of rapamycin complex 1 (mTORC1), and acts as an epigenetic regulator targeting TEAD4 to modulate oxidative phosphorylation (OXPHOS) in prostate cancer cells." (PMID 38104097, 2023). "In addition to TEAD4, TEAD1 expression is also associated with prostate cancer progression." (PMID 35602596, 2022). "Silencing of TEAD4 suppresses OXPHOS functions and prostate cancer cell growth in vitro and in vivo." (PMID 33893278, 2021). "TEAD4 is highly expressed in various prostate cancer cell lines but not in normal prostate cell line, RWPE1 cells." (PMID 33893278, 2021).
colon cancer (5 papers, 2016 to 2024). "One such targeted approach may be to direct therapies at disease-specific or sub-optimal splice variants of the Hippo pathway, such as the full length TEAD4 isoform seen in lung and colon cancer and the β, γ, and δ isoforms of YAP with affected TAD domains." (PMID 29534050, 2018). "Nevertheless, TEAD4 also can modulate the colon cancer progression in a YAP-independent manner." (PMID 35602596, 2022). "In colon cancer, TEAD4 may also form a complex with TCF3 under the regulation of Wnt." (PMID 39228892, 2024). "The regulatory function of TEAD4, TCF3, ETV4, SOX4, and FOXM1, over other key TFs and common DEGs, was highlighted in colon cancer, establishing key co-regulatory complexes." (PMID 39228892, 2024).
glioblastoma (5 papers, 2017 to 2025). The most malignant astrocytic tumor (WHO grade IV). "Four candidate transcription factors (GATAD1, TEAD4, IRF1, and EGR2) were finally obtained and were found to be considerably highly expressed in specimens of patients with glioblastoma according to the results of qRT‐PCR and western blot." (PMID 36987665, 2023).
breast tumors (3 papers, 2015 to 2023). "Similarly, we found that overall TEAD protein expression (using anti-TEAD4 antibody) was negatively associated with the patient age among the 121 primary breast tumor samples." (PMID 25970772, 2015). "Since the anti-TEAD4 antibody did not specifically recognize the TEAD4 protein by IHC in clinical samples, we analyzed the TEAD4 mRNA levels in breast tumors from the TCGA database." (PMID 25970772, 2015).
esophageal cancer (3 papers, 2021 to 2022). A primary or metastatic malignant neoplasm involving the esophagus. "The transcription factors LEF1, TEAD4, OCT4 and other molecules promote the biological behavior of esophageal cancer, and are associated with poor prognosis of esophageal cancer patients." (PMID 36611908, 2022). "BART results for up-regulated genes in stomach and esophageal carcinoma (STES) rank YAP1 and TEAD4 among the top three ranked putative TRs." (PMID 33778495, 2021).
esophageal squamous cell carcinoma (3 papers, 2021 to 2023). Esophageal squamous cell carcinoma (ESCC) is a type of esophageal carcinoma (EC) that can affect any part of the esophagus, but is usually located in the upper or middle third. "TEA domain transcription factor 4 (TEAD4) has been investigated to be implicated in the progression of various cancers, and it plays a role in the esophageal squamous cell carcinoma (ESCC)." (PMID 33517828, 2021). "Targeting TEAD4/YAP1 complex or SGK1 could find application in the treatment of esophageal squamous cell carcinoma." (PMID 33517828, 2021). "YAP1 induces KIF4A transcription by binding to the KIF4A promoter via TEA domain transcription factor 4 (TEAD4), contributing to the progression and poor prognosis of esophageal squamous cell carcinoma." (PMID 37039264, 2023).